MIR711 (microRNA 711)
Synonyms: hsa-mir-711
Gene: MicroRNA gene on chromosome 3 (48,578,902 to 48,578,977, reverse strand). Ensembl gene ENSG00000284251.
Gene Ontology:
Biological process: miRNA-mediated post-transcriptional gene silencing
Cellular component: RISC complex
Homologues: Orthologues: chimpanzee ptr-mir-711 (100% identical), macaque mml-mir-711 (100% identical), mouse Mir711 (86% identical), rat Mir711 (74% identical).